DBN1 (drebrin 1)
Diseases named in the same sentence as DBN1 in open-access papers:
DBN1 is named in the same sentence as 43 diseases in open-access papers, as found by Europe PMC text mining. Sharing a sentence is not in itself a finding about the gene and the disease. The quoted sentences say what the papers report.
lung adenocarcinoma (5 papers, 2020 to 2021). A carcinoma that arises from the lung and is characterized by the presence of malignant glandular epithelial cells. "Studies have shown that transcription factor AP-2 alpha (TFAP2α) promotes the proliferation, invasion, and metastasis of lung adenocarcinoma cells through ITPKA overexpression, which is induced by an interaction with Drebrin 1 (associated with cancer metastasis) and activation of EMT." (PMID 33988228, 2021). "Indeed, another study showed that cases with high DBN1 expression had a significantly poorer prognosis than those with low expression, suggesting it could act as a prognostic biomarker in lung adenocarcinoma." (PMID 32545448, 2020).
Alzheimer disease (4 papers, 2014 to 2023). A progressive, neurodegenerative disease characterized by loss of function and death of nerve cells in several areas of the brain leading to loss of cognitive function such as memory and language. "Although DBN1, a cytoplasmic actin-binding protein, is known to be expressed ubiquitously, its function has been documented mainly in neurobiology such as neuronal stem cell differentiation and cognitive function in Alzheimer’s disease." (PMID 36567320, 2022). "Alzheimer's disease cortex showed significantly increased mRNA and protein levels of IL-1β, TNFα, GFAP, CD11b, cPLA2 IVA sPLA2 IIA COX-1 and COX-2, but decreased levels of pre-synaptic synaptophysin (SYP) and post-synaptic drebrin (DBN1)." (PMID 25329999, 2014).
breast carcinoma (4 papers, 2007 to 2023). "In the mRNA cohorts, high DBN1 expression was associated with poor breast cancer specific survival and recurrence." (PMID 32545448, 2020). "Next, the association of DBN1 mRNA expression with the clinicopathological parameters in luminal breast cancer was investigated using the METABRIC cohort and validated by using the bc-GenExMiner dataset." (PMID 32545448, 2020). "Regarding luminal breast cancer subtypes, DBN1 protein expression was associated with poor patient outcome in the ER+ high proliferation/luminal B subtype." (PMID 32545448, 2020). "High DBN1 mRNA expression was significantly associated with increased risk of death, recurrence and distant metastasis among the endocrine-treated patients with luminal breast cancer." (PMID 32545448, 2020). "Overexpression of MID2 and DBN1 which are regarded as the top up-regulated hub genes in GSE76092 dataset is related to chemoresistance in breast cancer and leukemia, respectively." (PMID 37535601, 2023). "Our results further demonstrate that DBN1 is an independent prognostic marker in luminal breast cancer." (PMID 32545448, 2020). "DBN1 mRNA was highly expressed in 37% of luminal breast cancers from the METABRIC cohort, and its copy number gain was observed in 7.7% of cases, whereas 1.6% showed a copy number loss." (PMID 32545448, 2020). "The current study provides definitive evidence that DBN1 is an independent prognostic marker of poor clinical outcome in patients with luminal breast cancer." (PMID 32545448, 2020). "Its association with the response to endocrine therapy and outcome provides evidence for DBN1 as a potential biomarker in luminal breast cancer, particularly for the benefit of endocrine treatment." (PMID 32545448, 2020). "Also, DBN1 is an independent prognostic indicator for luminal breast cancer related to endocrine treatment response and prognosis." (PMID 33748290, 2021). "Our findings suggest that DBN1 expression could be used as a prognostic marker in luminal breast cancer and to better identify the appropriate patients whose tumours are most likely to benefit from endocrine therapy." (PMID 32545448, 2020). "Next, large, well-characterised cohorts of primary luminal breast cancer with long-term follow-up were assessed at the mRNA and protein levels for the value of DBN1 as a prognostic marker in luminal breast cancer, as well as its potential for predicting the benefit of endocrine therapy." (PMID 32545448, 2020). "For the mutome genes, the integrative analysis of genomic copy number and expression data strongly indicates that DBN1 is a candidate oncogene that, when highly expressed in tumors with respect to healthy tissues, predicts poor survival in breast cancer patients." (PMID 17280605, 2007). "As DBN1 was a key DEG in predicting response to adjuvant endocrine therapy, the clinical impact of its expression on luminal breast cancers was investigated." (PMID 32545448, 2020). "However, to date, the clinical significance of DBN1 in luminal breast cancer remains unclear." (PMID 32545448, 2020). "DBN1 protein expression was predominantly expressed in the cytoplasm of invasive breast cancer cells, with intensity levels varying from absent to high." (PMID 32545448, 2020).
cognitive decline (3 papers, 2017 to 2024). "Seven of the 22 peptides associated with the frail vs control diagnostic contrast and cognitive decline were cytoskeleton-related, including proteoforms of MAP2, VIM, TUBB, DBN1, TUBA8, PALM and NEFM." (PMID 38531951, 2024). "Numerous laboratory studies as well as human clinical evidence have demonstrated that decreased DBN1 expression in the brain results in cognitive decline." (PMID 31001081, 2019).
glioma (2 papers, 2016 to 2020). A benign or malignant brain and spinal cord tumor that arises from glial cells (astrocytes, oligodendrocytes, ependymal cells). "On the contrary, knockdown of DBN1 in glioma cells by small interfering RNA (siRNA) leads to decrease of cell migration and invasiveness." (PMID 28025492, 2016). "Additionally, it has been shown that knockdown of DBN1 decreased the invasion and migration of glioma cells, while DBN1 overexpression leads to alterations in cell morphology and induces increased invasiveness in vitro." (PMID 32545448, 2020).
melanoma (2 papers, 2021 to 2022). A malignant, usually aggressive tumor composed of atypical, neoplastic melanocytes. "Although there is no clear evidence to elucidate the relationship between drebrin 1 (DBN1), KDEL (Lys-Asp-Glu-Leu) containing 2 (KDELC2) with M2 macrophages and melanoma, studies have shown that DBN1 and KDELC2 play essential roles in other cancers." (PMID 33748290, 2021). "In summary, we found that NOTCH3, DBN1, KDELC2, and STAB1 were closely related to M2 macrophage infiltration in melanoma tissues." (PMID 33748290, 2021). "The yellow-green module was the coexpression module most related to M2 macrophages in TCGA-SKCM; NOTCH3, DBN1, KDELC2, and STAB1 were identified as the essential genes that promoted the infiltration of M2 macrophages in melanoma." (PMID 33748290, 2021). "In these studies, we demonstrated the role of NOTCH3, DBN1, KDELC2, and STAB1 in melanoma patients." (PMID 33748290, 2021).
acute myocardial infarction (1 paper, 2025). Necrosis of the myocardium, as a result of interruption of the blood supply to the area. "DBN1 and SLC2A3 are the final hub genes identified in our analysis, and they show potential as candidate biomarkers for the early diagnosis of acute myocardial infarction." (PMID 40672380, 2025). "Elevated expression levels of RAC1, IQGAP1, MYL6, DBN1, SLC2A1 and SLC2A3 were observed in acute myocardial infarction patients compared to healthy controls, suggesting a strong association with disease progression and indicating their potential as novel therapeutic targets." (PMID 40672380, 2025).
autoimmune disease (1 paper, 2023). A disorder resulting from loss of function or tissue destruction of an organ or multiple organs, arising from humoral or cellular immune responses of the individual to their own tissue constituents. "TREML1, CAPN1, and DBN1 seem the most relevant based on their functions in immune responses, cytoskeletal remodeling, cell adhesion/migration and association with chronic inflammatory and autoimmune diseases." (PMID 37205098, 2023).
breast tumours (1 paper, 2020). "In addition, our results indicated that expression of DBN1 has important effects on the clinical outcome of patients with luminal breast tumours." (PMID 32545448, 2020).
cholangiocarcinoma (1 paper, 2020). A carcinoma that arises from the intrahepatic biliary tree (intrahepatic cholangiocarcinoma) or from the junction, or adjacent to the junction, of the right and left hepatic ducts (hilar cholangiocarcinoma). "However, CD36, GGCX, UBASH3B, DBN1, PTTG1, CCNA2, and SPATS2 are found in other tumors to regulate tumor progression, which may also regulate cholangiocarcinoma progression and affect the recurrence of CCA." (PMID 32071556, 2020).
colon cancer (1 paper, 2021). "The low expression of the DBN1 gene may be related to colon cancer cells' resistance to vincristine." (PMID 33748290, 2021).
colorectal cancer (1 paper, 2021). A primary or metastatic malignant neoplasm that affects the colon or rectum. "Some authors used immunohistochemical techniques to measure the overexpression of DBN1 in colorectal cancer tissue lymph nodes and liver metastases in matching tissue sections." (PMID 33748290, 2021).
diabetes (1 paper, 2019). "Western blot analysis of isolated mouse glomeruli, however, showed that there were no alterations in the DBN1 levels in the diabetic mice or cultured podocytes under high-glucose conditions, consistent with the mRNA data of isolated glomeruli from other murine models of diabetes (nephroseq.org)." (PMID 31586053, 2019).
diabetic kidney disease (1 paper, 2024). Progressive kidney disorder caused by vascular damage to the glomerular capillaries, in patients with diabetes mellitus. "The decrease in DBN1 in human diabetic glomeruli may be due to podocyte loss during late diabetic kidney disease (DKD) rather than a decrease in the DBN1 gene itself." (PMID 39114368, 2024).
glaucoma (1 paper, 2019). Increased pressure in the eyeball due to obstruction of the outflow of aqueous humor. "To further explore the relationship between DBN1 levels and the severity of glaucoma, we divided glaucoma patients into two groups of DBN1-negative and DBN1-positive patients." (PMID 31001081, 2019). "In this study, we demonstrated that DBN1 plasma levels increased significantly in glaucoma patients with neurodegeneration and were correlated with RNFLD." (PMID 31001081, 2019). "Subsequently, we recruited over two hundred of glaucoma patients and measured DBN1 plasma levels." (PMID 31001081, 2019). "Thus, our data reveal that DBN1 plasma levels increased with axonopathy of glaucoma patients and then decreased with the progress of axonal degeneration." (PMID 31001081, 2019). "Our data suggest that DBN1 plasma levels may reflect the severity of RGC damage in glaucoma patients." (PMID 31001081, 2019). "In summary, we reported a novel finding that DBN1 plasma levels increased in glaucoma patients." (PMID 31001081, 2019). "Moreover, DBN1 plasma levels correlated with RNFLD in glaucoma patients and may reflect the severity of RGC injury." (PMID 31001081, 2019). "Subsequently, we recruited a total of 232 patients including primary angle-closure glaucoma (PACG), primary open-angle glaucoma (POAG) and Posner-Schlossman syndrome (PS) and measured its DBN1 plasma levels." (PMID 31001081, 2019). "To investigate the relationship between DBN1 plasma levels and RGC degeneration in glaucoma patients, we conducted OCT analysis and performed a correlation study." (PMID 31001081, 2019). "Taken together, our findings suggest that circulating DBN1 levels correlated with RNFLD and may reflect the severity of RGCs injury in glaucoma patients." (PMID 31001081, 2019). "In this study, we observed that DBN1 plasma levels increased significantly in glaucoma patients with RNFLD but not in patients without RNFLD or nonaxonopathic controls." (PMID 31001081, 2019). "However, the relationship between circulating DBN1 levels and RGC degeneration in glaucoma patients remains unclear." (PMID 31001081, 2019).
Hepatic fibrosis (1 paper, 2023). The presence of excessive fibrous connective tissue in the liver. "The qRT-PCR assays showed that Dbn1, Col1a1, and Col3a1 expression levels increased during CCl4-induced hepatic fibrosis." (PMID 36690273, 2023). "The temporal CDAHFD-feeding experiment revealed that Dbn1 expression was induced as the hepatic fibrosis progressed, along with increase in Col1a1 and Col3a1 expression." (PMID 36690273, 2023).
hypospadias (1 paper, 2022). Hypospadias is the displacement of the urethral meatus on the ventrum of the penis. "SRO018 is within this locus and is composed of only cases with duplications; this SRO contains candidate genes DBN1 and NSD1, which may contribute to hypospadias etiology in these cases." (PMID 35457073, 2022).
mantle cell lymphoma (1 paper, 2010). Mantle cell lymphoma is a rare form of malignant non-Hodgkin lymphoma affecting B lymphocytes in the lymph nodes in a region called the ``mantle zone''. "Among these genes, DBN1, SETMAR and HIG2 were found to be significantly correlated to SOX11 expression in two cohorts of primary mantle cell lymphomas." (PMID 21124928, 2010).
non-small cell lung carcinoma (1 paper, 2020). A group of at least three distinct histological types of lung cancer, including non-small cell squamous cell carcinoma, adenocarcinoma, and large cell carcinoma. "In a recent study of non-small cell lung cancer, DBN1 was reported as a genomic marker, exhibiting potential clinical utility for risk stratification of Stage I–III." (PMID 32545448, 2020).
optical neuropathy (1 paper, 2019). "To verify the expression of DBN1 proteins after RGC injury, we generated an ONC model, which is frequently used for optical neuropathy studies." (PMID 31001081, 2019).
Primary glaucoma (1 paper, 2019). "We observed elevated DBN1 plasma levels in patients with primary glaucoma but not in patients with PS compared to nonaxonopathic controls." (PMID 31001081, 2019).
prostate carcinoma (1 paper, 2020). A carcinoma that arises from epithelial cells of the prostate gland. "In prostate cancer, it has been shown that knockdown of DBN1 decreases the invasion of cell lines in 3D in vitro assays, whereas DBN1 overexpression enhanced it." (PMID 32545448, 2020).
cancer (9 papers, 2013 to 2024). A tumor composed of atypical neoplastic, often pleomorphic cells that invade other tissues. "Meanwhile, DBN1 was reported to be involved in actin cytoskeleton reorganization, which had a vital role during cancer metastasis." (PMID 32071556, 2020). "Mechanistically, ITPKA executed its action through the inducting of epithelial-mesenchymal transition (EMT) and interacting with Drebrin 1 (which is related to cancer metastasis)." (PMID 32015686, 2020). "DBN1 may play an essential role in cancer metastasis because actin recombination is an essential tumor cell migration and invasion process." (PMID 33748290, 2021). "Interestingly, DBN1 is thought to be a regulator of actin filament assembly, thereby contributing to cell motility and morphology, suggesting that DBN1 could deliver this role during cancer metastasis." (PMID 32545448, 2020). "ITPKA could influence cancer cell migration, invasion, and proliferation via EMT, and interacting with DBN1." (PMID 32015686, 2020). "However, DBN1 expression has been recently found in a wide variety of non-neuronal cells, including cancer cells." (PMID 32545448, 2020).
tumor (8 papers, 2007 to 2023). "The analysis revealed that patients with tumours that highly expressed DBN1 mRNA were associated with a shorter time to recurrence, distant metastasis and survival than those with low DBN1 expression (p < 0.05)." (PMID 32545448, 2020). "The ability of DBN1 in predicting the response of endocrine therapy was tested by analysing its association with clinical outcome in a subgroup of patients with luminal tumours who received adjuvant endocrine therapy alone." (PMID 32545448, 2020). "In the present study, we found that patients with high DBN1 expression was associated with a higher risk of distant metastasis than those with low expression, which supports the idea that DBN1 might associate with the invasive and migratory behaviour of tumours." (PMID 32545448, 2020). "For example, ACTN4 is involved in the formation of F-actin and the regulation of cell migration and tumor invasion, and DBN1 plays a role in cell migration and actin polymerization." (PMID 34726485, 2021). "Using multivariate Cox regression analysis, including tumour size, nodal stage and tumour grade, DBN1 protein expression, along with tumour size and nodal stage, was an independent prognostic marker for recurrence (p < 0.05)." (PMID 32545448, 2020). "In terms of clinical outcome, patients with higher DBN1 tumour levels in the METABRIC cohort had an unfavourable outcome compared with those patients with low DBN1 expression (p < 0.05)." (PMID 32545448, 2020). "Although some studies have revealed that both YAP and DBN1 could participate in tumor progression, it is currently unclear whether changes in the phosphorylation status of DBN1 results in functional changes." (PMID 38057879, 2023). "Indeed, analysis showed that DBN1 mRNA, along with tumour size and grade, independently predicted the distant metastasis and survival (p < 0.05)." (PMID 32545448, 2020). "Within the different molecular subtypes of luminal tumours, high DBN1 protein expression was associated with shorter survival in ER+ high proliferation/luminal B tumours (p < 0.05), but not for ER+ low proliferation/luminal A subtype (p = 0.7)." (PMID 32545448, 2020). "Multivariate analysis using the METABRIC cohort showed that DBN1 mRNA expression is independent of tumour size, nodal stage and tumour grade in predicting recurrence." (PMID 32545448, 2020).
neurodegenerative disease (1 paper, 2019). A disorder of the central nervous system characterized by gradual and progressive loss of neural tissue and neurologic function. "Developmentally regulated brain protein (Drebrin or DBN1) is an evolutionarily conserved actin-binding protein playing a prominent role in neurons and is implicated in neurodegenerative diseases." (PMID 31001081, 2019). "In conclusion, combining the measurement of circulating DBN1 and tau levels may be a useful indicator for the diagnosis or evaluation of the severity of axonopathy in neurodegenerative diseases." (PMID 31001081, 2019).
DBN1 also shares sentences with these, for which no sentence is quoted: Cognitive impairment (2 papers); schizophrenia (2); Stroke (2); Angelman syndrome (1); atherosclerosis (1); autism (1); COVID-19 (1); dementia (1); endothelial dysfunction (1); epilepsy (1); idiopathic cardiomyopathy (1); leukemia (1); Luminal Breast Cancer (1); mental illness (1); primary angle-closure glaucoma (1); primary open-angle glaucoma (1); Seizure (1); triple-negative breast carcinoma (1).